CACNB2 (calcium voltage-gated channel auxiliary subunit beta 2)
Diseases named in the same sentence as CACNB2 in open-access papers (continued):
Sharing a sentence is not in itself a finding about the gene and the disease.
bipolar disorder I (1 paper, 2014). "Previously, CACNB2 had been one of the top hit regions in a GWAS of bipolar disorder I in a Han Chinese population." (PMID 24901509, 2014).
cardiac conduction disease (1 paper, 2013). "Finally, CACNB2 is associated with the regulator of the voltage-gated calcium channels RIM1, and with the sodium channel SCN2B, through its interaction with CACNA1B, since it has been described that a mutation in CACNB2b, and a mutation in SCN5A underlie cardiac conduction disease.." (PMID 24339868, 2013).
fibrosis (1 paper, 2021). the formation of excess fibrous connective tissue in an organ or tissue in a reparative or reactive process. "Various genes which are potentially regulated by this miRNA are involved in calcium and potassium handling in myocytes (CACNB2, KCNN3), in protection of cells against oxidative stress (SIRT1), and in regulating cardiac fibrosis (STAT3)." (PMID 35052352, 2021).
gastric cancer (1 paper, 2024). A primary or metastatic malignant neoplasm involving the stomach. "The same authors reported that certain genes might be used as prognostic factors in H. pylori-positive gastric cancer patients (CACNB2, PREX1, MEF2C, GNB4, GRIN2A), while others (CACNB2 and MEF2C) predict the overall survival in these patients." (PMID 38255710, 2024).
heart hypertrophy (1 paper, 2021). "The transcription of Kcnj5, Cacnb2 and Cacna1c was reduced in the hearts of mice with severe heart hypertrophy." (PMID 34201741, 2021).
hyperthyroidism (1 paper, 2023). Overactivity of the thyroid gland resulting in overproduction of thyroid hormone and increased metabolic rate. "The corresponding mutated genes set that has common effects on hyperthyroidism in children included IGF1, CACNA1S, MYH7, IL6, TTN, CACNB2, LAMA2, and DMD." (PMID 37876543, 2023).
hypertrophic cardiomyopathy (1 paper, 2023). A condition in which the myocardium is hypertrophied without an obvious cause. "“Hypertrophic cardiomyopathy” in the signal pathway was followed with the p.adjust value of 1.10×10-3 and the corresponding collective action gene set with mutations included 8 genes: IGF1, CACNA1S, MYH7, IL6, TTN, CACNB2, LAMA2, DMD." (PMID 37876543, 2023).
memory impairment (1 paper, 2025). "In E3 mice, the combination of O3-induced BBB disruption and impaired calcium homeostasis (Cacnb2 downregulation) likely exacerbates excitotoxic damage, leading to memory impairment." (PMID 40141051, 2025).
Myocardial fibrosis (1 paper, 2022). "The decreased expression of CACNB2 led to the decrease in L-type current, promoted myocardial fibrosis, and accelerated myocardial electrical remodeling." (PMID 35669184, 2022).
preeclampsia (1 paper, 2026). Preeclampsia is a hypertensive disorder of pregnancy that is characterized by new-onset hypertension with proteinuria presenting after 20 weeks of gestation, and depending on mild or severe forms may initially present with severe headache, visual disturbances, and hyperreflexia. "For example, CACNB2-instrumented lowering corresponded to a 7% (95% CI: 5-9%) reduction in preeclampsia risk per 1 mmHg decrease in blood pressure." (PMID 42238470, 2026).
sudden cardiac arrest (1 paper, 2013). Unexpected rapid natural death due to cardiovascular collapse within one hour of initial symptoms. "CACNB2 is a subunit of a voltage-dependent calcium channel protein and mutations in CACNB2 were also associated with sudden cardiac arrest." (PMID 24358131, 2013).
psychiatric disorder (16 papers, 2014 to 2024). A disorder characterized by behavioral and/or psychological abnormalities, often accompanied by physical symptoms. "Similar to CACNA1C, SNPs in CACNB2 have shown strong association with BD and other psychiatric disorders." (PMID 31331039, 2019). "Polymorphisms in CACNA1A and CACNB2 were demonstrated to be trans-diagnostic markers of major psychiatric disorders." (PMID 27091189, 2016). "Recently, CACNB2 was found as a risk locus for five major psychiatric disorders including ASD and thus is regarded as a susceptibility gene." (PMID 24752249, 2014). "Dysregulation of cellular calcium homeostasis might be involved in ASD pathogenesis, and genes coding for the L-type calcium channel subunits CaV1.2 (CACNA1C) and CaVβ2 (CACNB2) were recently identified as risk loci for psychiatric diseases." (PMID 24752249, 2014). "CACNB2, together with CACNA1C, is one of most consistently found risk genes for psychiatric disorders, particularly SCZ and BD." (PMID 31331039, 2019).
tumor (4 papers, 2021 to 2026). "By combining these gene sets, we identified the leading genes that were associated with the tumor laterality: CACNA1C, CACNA2D2, CACNB2, KCNJ11, SCN3A, and SCN3B, signature that we called: 6-ICH signature." (PMID 37446299, 2023). "In contrast, the expression of genes, including STAG3, GATA5, and CACNB2, which are associated with cell proliferation or tumorigenesis, and PRAP1, which is primarily involved in the inhibition of tumor cell apoptosis, increased in mouse KrasG12D/Galc KO pancreatic organoids." (PMID 37848935, 2023). "Seven genes (CACNB2, IL34, CGNL1, CNTN3, GAS7, HOPX, and PBX1) regulated by miR-31-5p and miR-31-3p were identified as putative tumor suppressors." (PMID 34201353, 2021).
cancer (3 papers, 2020 to 2022). A tumor composed of atypical neoplastic, often pleomorphic cells that invade other tissues. "Three of these (lnc-SPG21-45, lnc-NSUN6-1 and lnc-KLHL28-1) are antisense to ANKDD1A, CACNB2 and C14orf28 genes, respectively, which are associated with other cancers and diseases, possibly by regulating their expression." (PMID 33245713, 2020). "For the hyper-methylated gDMs, down-regulated expression in cancer samples was observed for CACNB2 and ZIC1." (PMID 36329447, 2022). "We found that the targets of nifedipine, such as voltage-dependent L-type calcium channel subunit alpha-1C (CACNA1C), subunit alpha-1D (CACNA1D) and beta-2 (CACNB2), have important links to cancer development and progression." (PMID 33893730, 2021).
brain diseases (1 paper, 2020). "CACNA1C (rs1024582) and CACNB2 (rs2799573) polymorphisms were suggested as the common risks across seven brain diseases." (PMID 33338084, 2020).
CACNB2 also shares sentences with these, for which no sentence is quoted: attention deficit-hyperactivity disorder (5 papers); autism spectrum disorder (5); cardiomyopathy (3); cardiovascular disease (3); cardiac arrhythmia (2); migraine (2); neurological disorders (2); Angelman syndrome (1); Anxiety (1); bladder cancer (1); chronic atrial fibrillation (1); developmental delay (1); diarrhoea (1); early repolarization syndrome (1); familial atrial fibrillation (1); Fever (1); gastroesophageal reflux disease (1); genetic disease (1); heart disease (1); Intellectual disability (1); Obesity (1); obsessive-compulsive disorder (1); Paralytic ileus (1); Parkinson disease (1); psychotic disorder (1); retinitis pigmentosa (1); Stillbirth (1); type 1 diabetes (1); type 2 diabetes mellitus (1); ventricular fibrillation (1).
A further 1 disease shares a sentence with CACNB2 in 1 paper.